MTOR (mechanistic target of rapamycin kinase)
Diseases named in the same sentence as MTOR in open-access papers (continued):
Sharing a sentence is not in itself a finding about the gene and the disease.
cancer (continued). "Rapamycin (SirolimusTM) was originally used as an immunosuppressant, but with the characterization of the mTOR growth pathway and its role in diseases, particularly cancer, its use widened." (PMID 33668092, 2021). "Pan-cancer analyses utilizing large in vitro and clinical datasets suggest a strong correlation between NFATc2 expression and mTOR pathway activation." (PMID 34021224, 2021). "PINK1 interacts with the oncogenic PI3K/Akt/mTOR signaling axis at multiple levels and controls the regulation of cancer survival and growth." (PMID 33981484, 2021). "In many cancer cells, the mTOR and Wnt pathways are synergistic for growth, and when one pathway is inhibited by drug treatment, the other becomes activated." (PMID 33668092, 2021). "Accumulating evidence shows that a large number of miRNAs act opposingly on the mTOR pathway, which is often hyperactivated in cancers." (PMID 34869377, 2021). "The PIK3/AKT/MTOR (phosphatidylinositol-4,5-bisphosphate 3-kinase/AKT serine-threonine kinase/mechanistic target of rapamycin kinase) is one of the most activated cell signaling routes in cancer." (PMID 34440837, 2021). "Growing evidence supports the role of mTOR is in cancer cell invasion and metastasis especially by regulating the organization of actin cytoskeleton." (PMID 33546106, 2021). "mTOR represents a functionally validated miR-99a target in several cancer cell lines and primary cells, but the interaction between miR-99a and mTOR expression or mTORC1 activity was not investigated in placental tissue or cell lines thus far." (PMID 33657992, 2021). "Polyphenols inhibit the PI3K/Akt/mTOR pathway; however, these agents can interfere with other signaling cascades involved in cancer progression, such as MAPK and oncogenic RAS." (PMID 34744708, 2021). "Others have shown that mTOR is modulated by perturbation in one carbon metabolism and, more specifically, in folate availability in cancer." (PMID 35010891, 2021). "Recent life science studies have proposed that aberrant PI3K/AKT/mTOR signaling pathway activation is the key to the shortened life cycle of cancer patients and that aberrant activation of this pathway is a vital mechanism of resistance to targeted therapies." (PMID 34135756, 2021). "Many clinical reports have attempted to investigate the roles and the potential prognostic value of mTOR and p-mTOR in a variety of cancers." (PMID 33572326, 2021). "The PI3K/Akt/mTOR axis, the most commonly hyperactivated pathway of human cancers, plays a pivotal role in promoting cell growth, proliferation, and survival and acting as a negative regulator of autophagy." (PMID 34691211, 2021). "The Wnt signaling pathway and mTOR signaling pathway have been widely reported to be related to cancer progression, and these two pathways have been reported to be related to tumor immune escape and immune checkpoint inhibitor resistance." (PMID 34922547, 2021). "Next, previous findings demonstrated that overexpression of miR-34a possesses tumor-suppressive functions via upregulating PTEN expression that acts as a critical negative regulator of PI3K/mTOR/AKT pathway in cancer cells." (PMID 33796457, 2021). "More importantly, substantial evidence has elucidated that mTOR acts as an oncogene in various cancers through activation its downstream molecule such as p70S6K and 4E-BP1." (PMID 33928514, 2021). "Overall, the analysis confirmed the extensive molecular heterogeneity of TNBCs and the prevalence of the PI3 K/AKT/mTOR signaling axis in these cancers." (PMID 34685748, 2021). "We conclude that therapeutic blockade of mTOR is sufficient to inhibit cancer stemness in MEC by mediating selective ablation of CSCs." (PMID 33479203, 2021). "Recently, several mTOR inhibitors have been approved by the U.S. Food and Drug Administration to treat different types of cancers." (PMID 34304249, 2021).
cancer (continued). "The role of the phosphoinositide 3-kinase (PI3K), AKT (also known as protein kinase B) and mammalian target of rapamycin (mTOR) pathway in cancer, is well established." (PMID 33546207, 2021). "The mTOR pathways typically are upregulated in cancers (including gastric, prostate and breast) and have been shown to contribute to cancer progression and metastasis." (PMID 34265852, 2021). "We have comprehensively reviewed cancer-related racial disparities and the expression or activation status of the upstream regulator and downstream effector proteins that regulate the mTOR and ERK-1/2 pathway." (PMID 33996789, 2021). "We envision that untangling these functional connections will be key for the generation of combinatorial anti-cancer therapies involving pro-senescence drugs, mTOR inhibitors, and/or autophagy inhibitors." (PMID 34360912, 2021). "Along with a continual production of lactate, cancer cells often maintain hyperactivation of the PAM (PI3K/AKT/mTOR) pathway." (PMID 33472174, 2021). "Critical downstream effector of the Akt is the mammalian target of rapamycin (mTOR), which is upregulated in many cancers." (PMID 33777761, 2021). "The cancer cell has the character of migration and invasion, which was regulated by the signaling pathway of mTOR/AKT/PI3K." (PMID 34840573, 2021). "The P13/AKT/mTOR axis, a commonly dysregulated pathway in cancer, is responsible for the regulation of cell growth and survival, and is one pathway activated by the binding of cannabinoids to their receptors." (PMID 33802014, 2021). "We previously showed that prolonged inhibition of mTOR improved sensitivity to radiation of radioresistant cancer cells to be conditioned to enter autophagy-prone senescence." (PMID 33674559, 2021). "In numerous cancer types, perturbations of PTEN regulation or PTEN loss-of-function mutations consequently result in upregulation of PI3K/Akt/mTOR signaling which contributes, to tumorigenesis." (PMID 35250965, 2021). "The compounds with the best efficiencies on PI3K and mTOR induced micromolar cytotoxicity on cancer cell lines possessing an overactivated PI3K pathway." (PMID 34500781, 2021). "We revealed that, after the treatment, a decrease in the AKT/mTOR signaling cascade was more pronounced in IHC PD-L1 positive cancers." (PMID 34681840, 2021). "mTOR inhibitors induce autophagy which is accompanied by increasing autophagosomes, and in addition, chronic treatment can lead to cell death in cancers, as well." (PMID 34360785, 2021). "Magnolol can negatively control HIF-1α expression by interfering with the PI3K/AKT/mTOR pathway under hypoxia, hence suppressing angiogenesis and cancer growth in vivo." (PMID 34575983, 2021). "Given how frequently the PI3K/mTOR pathway is altered in cancer, it is critical that we continue to investigate and uncover all of the possible feedback mechanisms and pathway interactions." (PMID 34203293, 2021). "We also identified some novel mutations in genes that are closely related to DNA repair-, cancer- or metabolism-related signaling pathways, including PI3K/Akt, mTOR, AMPK, FoxO, and insulin signaling." (PMID 34805171, 2021). "An analysis of the COSMIC database revealed an overexpression of MTOR in ovary (9.77%), urinary tract (8.33%), and skin (8.25%) cancers and a downregulation in tumors of the central nervous system (13.06%)." (PMID 33572326, 2021). "Based on these results, we suggest considering inducing metabolic stress and targeting mTOR hyperactivity and mitochondrial functions in combined anti-cancer treatments." (PMID 34360785, 2021). "The serine/threonine kinase mechanistic target of rapamycin (mTOR) is a central regulator of cellular metabolism, and its dysfunction is frequently observed in cancer." (PMID 34634301, 2021).
cancer (continued). "In this line, challenging the PI3K/mTOR pathway using inhibitors has been proposed to be a valuable tool for the treatment of cancer." (PMID 34074034, 2021). "Transcriptome analysis of USO1-depleted SEM cells in our study demonstrated a mixed picture, with the downregulation of certain cancer and cell growth-related pathways, including mTOR and ERB2, but concurrent downregulation of RNA metabolism and MYC targets." (PMID 34162911, 2021). "The remaining genes were involved in a wide range of cancer-related pathways, such as DNA replication, Ras signaling, and mTOR signaling." (PMID 34659209, 2021). "One of well-known signaling pathways related to cancer is the PI3K/AKT/mTOR pathway which has been proposed for the development of specific PI3K, Akt, and mTOR inhibitors in cancer treatment." (PMID 34360679, 2021). "Some mTOR inhibitors have been approved by the FDA to treat cancer, but a high number of them are still under investigation in many clinical trials." (PMID 33918514, 2021). "BCAT1 regulates mTOR-mediated autophagy via branched-chain amino acid metabolism, thus reducing the sensitivity of cancer cells to cisplatin." (PMID 34976806, 2021). "In addition to relaying the oncogenic signals from the upstream PI3K/AKT pathway in various cancers, mTOR may play a direct role in human tumorigenesis if mutated, including in BC, which further support the view of mTOR as one of the major therapeutic target against cancer." (PMID 33494738, 2021). "Critically, many compounds that can suppress immunity are also antiproliferative; for instance, rapamycin, which modulates mTOR, is well known to be activated in cancer and a modulator of mitochondrial function." (PMID 34046425, 2021). "The PI3K/Akt/mTOR pathway plays a major role in survival, growth, metastasis, and drug chemoresistance in cancer." (PMID 34744708, 2021). "Another is a phase I/II study (NCT02208375), in which olaparib plus AZD 2014 (mTOR inhibitor) or AZD5363 (AKT inhibitor) regimens are being assessed in several types of cancers, including TNBC." (PMID 33790792, 2021). "These affected metabolites were found to be involved in the central carbon metabolism in cancer, the mTOR signaling pathway, and the choline metabolism in cancer." (PMID 33933119, 2021). "Despite AKT/mTOR inhibition being an important strategy for cancer treatment, some mTOR inhibitors, such as ‘rapalogs’, presented a feedback loop activation of the AKT/mTOR axis, becoming cytostatic rather than cytotoxic." (PMID 33918290, 2021). "The aim of this study was to investigate the PI3K/PTEN/Akt/mTOR pathway as one of the most frequently deregulated pathways in cancer." (PMID 34833123, 2021). "Many studies on the PI3K/AKT/mTOR pathway in CAFs have shown that activation of this cascade promoted various cancer behaviors, especially cell proliferation." (PMID 34108441, 2021). "Herein, our data suggested that MAPK, mTOR, pathways in cancer, PPAR, TGF-beta, and WNT signaling pathways were enriched in the high-risk group." (PMID 33928101, 2021). "Given that activation of PI3K/AKT/mTOR promotes tumour growth, metastasis, and resistance to anticancer therapies, mTOR inhibitors show promise in the treatment of cancer." (PMID 34768941, 2021). "We have also discussed potential biomarkers involved in pathways that are differentially affected or modified during the onset of HPV-related cancers, such as Akt, mTOR, miRNAs, TNF-α, TGF-β, BRCA1, and FANCD2." (PMID 33668730, 2021). "We also present recent data regarding the PI3K/AKT/mTOR inhibitors in clinical studies and the treatment of cancer, as well the attendant problems of resistance and adverse effects." (PMID 33572326, 2021). "Collectively, our data reveal that oncogenic KRAS alters the expression of AATs such as SLC1A5/ASCT2, SLC7A5/LAT1, and SLC38A2/SNAT2 and thereby increase the uptake of AAs to support cancer cell proliferation through mTOR activation." (PMID 34003553, 2021).
cancer (continued). "The PI3K/AKT/mTOR signaling pathway is known to control cell survival and is abnormally activated in a wide variety of cancers, resulting in inhibition of apoptosis via multiple mechanisms." (PMID 33549034, 2021). "Some of the commonly used anti-cancer drugs, including cisplatin, gemcitabine, and paclitaxel, as well as mTOR suppressor OSI_027, exhibited significant different pharmacological effect in the two metabolic subtypes." (PMID 34030708, 2021). "In this study, we explored the expression of mTOR pathway genes in a variety of cancers and the potential compounds that target the mTOR pathway and focused on an abnormal type of cancer, kidney renal clear cell carcinoma (KIRC)." (PMID 34194607, 2021). "CD44 regulates the phosphoinositide-3-kinase (PI3K)/AKT/mTOR signaling pathway and promotes cancer cell migration." (PMID 33925400, 2021). "Previous studies have investigated antiparasitic agents, including itraconazole and ivermectin, which block the Akt/mTOR pathway, thereby inducing autophagy and leading to cancer cell death." (PMID 35096055, 2021). "The association of lower plasma levels of miR-451 in advanced stages of ccRCC was explained by its tumor suppressor activity, involved in the regulation of the PI3K/Akt/mTOR signaling pathway in different types of cancer." (PMID 34440329, 2021). "miR-873-5p can affect the occurrence and development of cancer by participating in the PIK3/AKT/mTOR, Wnt/β-Catenin, NF-κβ, MEK/ERK, and other signaling pathways." (PMID 34676171, 2021). "Other pathways commonly associated with cancer, such as EGFR, MAPK, mTOR, and PI3K-Akt, were also significantly enriched." (PMID 34104084, 2021). "A recent pan-cancer study identified signaling via SHC family adapter proteins and PI3K/Akt/mTOR among the pathways highly mutated in cancer." (PMID 33673232, 2021). "Cellular pathways, like the PI3K/AKT/mTOR signaling pathway, is an attractive candidate because there are numerous established drugs that inhibit this pathway for cancer treatment." (PMID 34831441, 2021). "The Akt/mTOR pathway is a key signaling cascade that is activated in a variety of cancers, and its activation can prompt cancer development." (PMID 33708631, 2021). "To date, several signaling pathways regulating autophagy have been identified, including mTOR, PI3K/AKT, and ROS signaling pathways, among which the mTOR pathway plays a significant role in cancer-related autophagy." (PMID 34093717, 2021). "In this case, mTOR is important as cancer cells reprogram their metabolism to be sustained even with scarce nutrients or in stressful environments." (PMID 33916290, 2021). "The PI3K/AKT/mTOR signaling pathway is also studied in cancer since it regulates cell proliferation, growth, metabolism and motility." (PMID 34305611, 2021). "The mechanistic target of rapamycin (mTOR) kinase plays a fundamental role in promoting cellular anabolism and is often hyperactive in cancer cells." (PMID 33219129, 2021). "For example, the PI3K/Akt-mTOR pathway, which is typically altered in cancers—including OS—, upregulates cellular glucose uptake, while oncogenes c-MYC and hypoxia-inducible factor-1 (HIF-1) upregulate glycolytic enzymes." (PMID 34715874, 2021). "A few studies have investigated the immune effects of mTOR inhibitors in cancer patients and have confirmed the bimodal activity observed in murine models." (PMID 33802831, 2021). "Cellular signaling in cancers results in the depression of the AKT/mTOR signaling pathway and the activation of transcriptional and growth factors." (PMID 34681840, 2021). "ITGB3 is a regulator of the PI3K/AKT/mTOR pathway and has roles in cancer and extracellular vesicles that induce cell signaling." (PMID 34831441, 2021). "The mammalian target of rapamycin (mTOR) signaling pathway plays an important role in the development of many cancers." (PMID 33754064, 2021).
cancer (continued). "The top 20 significantly enriched pathways included neuroactive ligand-receptor interaction (hsa04080), PI3K-Akt signaling pathway (hsa04151), pathways in cancer (hsa05200), dopaminergic synapse (hsa04728), and mTOR signaling pathway (hsa04150)." (PMID 34976096, 2021). "For instance, the prosurvival effect that FN1 has on cancer cells is primarily mediated by FAK-dependent activation of the PI3K/AKT/mTOR pathway." (PMID 34758823, 2021). "At concentrations that also inhibit the PI3K/Akt/mTOR-signaling pathway, quercetin suppresses cancer cell growth." (PMID 34504654, 2021). "The activation of the AKT/mTOR signaling pathway is thought to enhance cancer cell proliferation in LSCC." (PMID 34257531, 2021). "Further, the MAPK and PI3K/Akt/mTOR signaling pathways have been shown to activate NF-κB in numerous cancer cell lines by modulating several phytochemicals in the autophagy-apoptosis pathway." (PMID 34025409, 2021). "Herein we demonstrate that that mTOR inhibitors and auranofin synergize to induce cancer cell death by inducing oxidative stress." (PMID 33754064, 2021). "Mammalian target of rapamycin (mTOR), a serine/threonine kinase involved in cell proliferation, survival, metabolism and immunity, was reportedly activated in various cancers." (PMID 34458019, 2021). "The PI3K/AKT/mTOR signaling pathway is involved in cell proliferation, growth, differentiation, and cytoskeletal reorganization in many types of cancer 39-41." (PMID 34234863, 2021). "PI3K/Akt/mTOR signaling pathways are crucial to multiple aspects of cell growth and survival in physiological and pathological conditions, such as cancer." (PMID 34830339, 2021). "In correlation with this, tumor cell lines have higher mTOR activity than their original in vivo tumor tissue counterparts (xenograft or human cancers in situ)." (PMID 35029792, 2021). "Compared to rapamycin or to the kinase inhibitor of mTOR sapanisertib, RapaLink-1 provides a stronger anti-cancer effect in different glioblastoma models." (PMID 33802831, 2021). "mTOR inhibitors have thus been widely studied for their use in cancer treatment, and some of these inhibitors (e." (PMID 34123955, 2021). "As shown in the resulting figure, since the mTOR pathway itself is a cancer pathway, related genes are present as risky genes in most cancers." (PMID 34194607, 2021). "Let‐7e‐5p, miR‐125a‐5p, miR‐99b‐5p, miR‐150‐5p, miR‐378a‐3p were the most abundant enriched miRNAs in EV extracts compared to total blood plasma and associated with cancer related pathways including PI3K‐AKT and mTOR." (PMID 34429857, 2021). "According to the KEGG pathway analysis, DDIT4 was found to be related to PI3k-Akt/mTOR signaling and microRNAs in cancer pathway, as a part of CRC disease using the KEGG DISEASE Database." (PMID 34211002, 2021). "In cancer cells dysregulation of the PI3K/Akt or the Ras/ERK signaling are coupled to mTOR activation which controls differentiation, proliferation, survival, cytoskeleton organization and autophagy." (PMID 34572839, 2021). "The PI3K/AKT/mTOR intracellular signalling pathway is important in regulating the cell cycle, with mTOR activity, a common target for cancer therapeutics, being frequently upregulated across multiple cancer types." (PMID 34944870, 2021). "The phosphatidylinositol 3-kinase (PI3K)/protein kinase B (AKT)/mammalian target of rapamycin (mTOR) signaling pathway plays an important role in carcinogenesis, which is abnormally activated in various types of cancer." (PMID 34381313, 2021). "mTOR regulates several processes that control tumor development, including cancer cell growth, angiogenesis and the immune response to tumor." (PMID 33802831, 2021).